NEAT1 (nuclear paraspeckle assembly transcript 1)
Diseases named in the same sentence as NEAT1 in open-access papers (continued):
Sharing a sentence is not in itself a finding about the gene and the disease.
asthma (19 papers, 2019 to 2025). "lnc-NEAT1 drives the inflammatory cytokine release and is linked to a higher risk of severe asthma exacerbations." (PMID 40806181, 2025). "Through its association with miR‐124, lnc‐NEAT1 triggers the release of a number of inflammatory cytokines, and it is linked to a high risk of severe asthma exacerbations." (PMID 38270295, 2024). "Clinically, NEAT1 correlated with increased exacerbation risk, severity, and inflammation in asthma and with worse disease condition and poor recurrence-free survival in acute ischemic stroke." (PMID 36552736, 2022). "Recent evidence indicates that the lnc‐NEAT1 expression is positively associated with disease severity in asthma patients and other allergic diseases." (PMID 35064698, 2022). "Long noncoding RNA nuclear enriched abundant transcript 1 (lnc‐NEAT1), located on chromatin 11, is a vital component of nuclear paraspeckles and implicated in the progression of many inflammation‐related diseases, such as sepsis and asthma." (PMID 35064698, 2022). "Down-regulation of NEAT1 reduced the Six1 expression via targeting miR-204-5p to inhibit the process of EMT in asthma." (PMID 39423195, 2024). "In the network, the lncRNAs KCNQ1OT1 and NEAT1 compete with all miRNAs and have the potential to be key targets in the treatment of AR and asthma." (PMID 36733482, 2023). "For instance, lnc‐NEAT1 has pro‐inflammatory biological property and promotes the secretion of many inflammatory cytokines in asthma via activating multiple signaling pathways." (PMID 35064698, 2022). "The up-regulation of NEAT1 occurs in the tissues of patients with asthma, COPD, and acute kidney injury." (PMID 35034548, 2022). "Some of them have been reported to be significantly relevant to asthma such as NEAT1 → hsa-miR-139→ JAK3." (PMID 34970542, 2021). "Li and coworkers found that lncRNA NEAT1 expression was negatively correlated with miR-124 in asthma patients." (PMID 34635022, 2021). "In the past, LncRNA nuclear-enriched abundant transcript 1 (lncRNA NEAT1) showed a significant role in adult asthma." (PMID 33925009, 2021). "Recently, Zhumx and colleagues demonstrated that the expression of lncRNA NEAT1 was increased and that of miR-139 was decreased in the ASMCs of asthma patients." (PMID 34635022, 2021). "Similarly, the expression of NEAT1 is significantly upregulated in CD4+ T cells in the peripheral blood of children with asthma." (PMID 40362651, 2025). "LncRNA NEAT1 was reported to participate in the process of fibrosis in asthma." (PMID 39423195, 2024). "Recent research has also highlighted the role of NEAT1 in asthma." (PMID 39423195, 2024). "The role of NEAT1 in smooth muscle cells was evaluated in some previous studies across various diseases, including abdominal aortic aneurysm, pulmonary hypertension, and asthma." (PMID 38646788, 2024). "The NEAT1/miR-204-5p/Six1 axis awaits validation in animal models and asthma-specific contexts." (PMID 39423195, 2024). "In a study involving 170 patients with asthma in exacerbation, 170 patients with asthma in remission, and 170 healthy controls, the expression of NEAT1 was significantly increased in patients with asthma in exacerbation or remission compared with healthy controls." (PMID 39423195, 2024). "It has also been demonstrated that lncRNA NEAT1 may be involved in the aggravation of asthma by sponging miR-124." (PMID 34635022, 2021). "Moreover, it was found that miR-24 was inversely associated with asthma attacks and inflammation, so it is likely that lncRNA NEAT1 might contribute to asthma pathogenesis via interaction with miR-124." (PMID 33925009, 2021). "We found that the expression of NEAT1 was upregulated during the EMT process, aligning with prior research, indicating its involvement in asthma." (PMID 39423195, 2024).
asthma (continued). "Although the composition of the cell subsets was similar between the groups, increased expression of JAK1, the long noncoding RNA NEAT1, and IL32 was noted in specific cell types of patients with severe asthma." (PMID 39672815, 2024). "The expression of NEAT1 and PINT (AC058791.2) is upregulated in children with therapy-resistant asthma." (PMID 30941157, 2019). "The upstream lnc NEAT1 was identified to modulate SLC26A2 expression by targeting miR‐9‐5p, enhance ASM cell proliferation, migration, contraction, and boost inflammation in child asthma patients." (PMID 38270295, 2024). "Taken together, the current results preliminarily suggested that lncRNA NEAT1 played a critical role in EMT via the miR-204-5p/Six1 axis, which provides new therapeutic targets for asthma patients and potentially improves asthma management and patient outcomes." (PMID 39423195, 2024). "Several studies on multiple sclerosis and asthma found that MALAT1 and NEAT1 regulate the RUNX3–GATA3/TBX21 axis, key transcription factors (TFs) in T cell differentiation, by regulating the expression levels of the related miRs, thereby influencing the direction of the Th1/Th2 bias." (PMID 38006062, 2023). "From this, it can be inferred that lncRNA NEAT1 plays an important role in ASMCs inflammation through regulating miR-139/JAK3/STAT5 signaling axis, and may become a target for asthma therapy." (PMID 34635022, 2021).
leukemia (19 papers, 2014 to 2025). A malignant (clonal) hematologic disorder, involving hematopoietic stem cells and characterized by the presence of primitive or atypical myeloid or lymphoid cells in the bone marrow and the blood. "LncRNAs have been implicated in the initiation and progression of leukemia, NEAT1 (nuclear paraspeckle assembly transcript 1) is correlated with the poor progression in CML and with multidrug resistance in pediatric acute lymphocytic leukemia." (PMID 39450252, 2024). "In hematological malignancies, Neat1 has previously been described as a tumor suppressor, with reduced expression associated with multidrug resistance in leukemia and impairment of myeloid differentiation in acute promyelocytic leukemia." (PMID 33154494, 2020). "To verify the biological significance of the lincRNA–promoter network, we found that two genes closely related to the differentiation of leukemia cells, NEAT1 and MALAT1, interact closely at the chromatin level." (PMID 40699783, 2025). "The frequent contact between MALAT1 and NEAT1 in 3D space is potentially related to the functional interaction between these two proteins in leukemia cells." (PMID 40699783, 2025). "NEAT1 is found to be highly expressed in most malignant tumors, yet current research shows its downregulation in leukemia and renal cancer, suggesting NEAT1’s varying roles across different tumors, which warrants further investigation." (PMID 40486880, 2025). "The most known examples are MALAT1 and NEAT1 expressed in different neoplasms, including B-cell lymphomas and leukemias." (PMID 36275462, 2022). "While the physical interaction of lncRNA MALAT1 with the SIPA1 leukemia oncogene has been experimentally validated and recapitulated in our network, MALAT1 is linked to other crucial oncogenes in the two linked modules, and co-expressed with NEAT1, another well-known lncRNA in the context of cancer." (PMID 31142264, 2019). "Thus, apart from the leukemia, NEAT1 mainly functions as an oncogene in solid tumor, including OS." (PMID 29654165, 2018). "After transfecting a NEAT1 plasmid into leukemia cell lines, the authors demonstrated that over-expression of NEAT1 could promote cell apoptosis and enhance the sensitivity of chemotherapy in leukemia cells." (PMID 28118609, 2017). "Additionally, they found elevated levels of miR-23a-3p, which indicate that NEAT1 binds miR-23a-3p to regulate SMC1A expression, thereby inhibiting leukemia cell proliferation and enhancing apoptosis." (PMID 32368311, 2020). "Apart from the included studies for solid tumors, NEAT1 was also found to have regulatory role in leukemia, however, the lack of relevant clinical data precluded it from meta-analysis in the present study." (PMID 27926523, 2017).
amyotrophic lateral sclerosis (17 papers, 2017 to 2025). Amyotrophic lateral sclerosis (ALS) is a neurodegenerative disease characterized by progressive muscular paralysis reflecting degeneration of motor neurons in the primary motor cortex, corticospinal tracts, brainstem and spinal cord. "NEAT1 expression variations have been associated to neurodegenerative illnesses such as amyotrophic lateral sclerosis and PD." (PMID 40407589, 2025). "A study showed that in the early stages of amyotrophic lateral sclerosis (ALS) NEAT1 expression is induced in the motor neurons." (PMID 30871545, 2019). "Similarly, NEAT1 has been proposed to have a dual role in the motoneuron disease amyotrophic lateral sclerosis (ALS)." (PMID 40234480, 2025). "TDP-43 has been associated with the development of amyotrophic lateral sclerosis (ALS) and an ALS-related mutation (D169G) of TDP-43 has been shown to impair NEAT1-mediated LLPS and nuclear body formation, resulting in an accumulation of TDP-43 in stress granules instead." (PMID 37782337, 2024). "Interestingly, both MALAT1 and NEAT1 are also deregulated in amyotrophic lateral sclerosis (ALS), which is a fatal neurodegenerative disorder characterized by progressive degeneration of motor neurons in the spinal cord, brainstem, and motor cortex." (PMID 35796900, 2022). "An increase in paraspeckles formation and NEAT1 levels has been detected in spinal motor neurons of early phase amyotrophic lateral sclerosis (ALS) patients compared to control individuals and compromised paraspeckles formation has been proposed as a pathogenic factor in FUSopathies." (PMID 29997370, 2018).
renal cell carcinoma (17 papers, 2017 to 2024). "Another group also found an elevation of mutations in the NEAT1 promoter in renal cell carcinoma, and these mutations were associated with increased NEAT1 expression and unfavorable patient survival." (PMID 30374364, 2018). "For example, NEAT1 could promote renal cell carcinoma (RCC) progression through the miR-34a/c-Met axis." (PMID 32596382, 2020). "Although the lncRNA nuclear enriched abundant transcript 1 (NEAT1) has been associated with tumorigenesis, its functions in renal cell carcinoma (RCC) have not been elucidated." (PMID 28968960, 2017). "For instance, a study demonstrated that NEAT1 promotes EMT and sorafenib resistance in renal cell carcinoma through the miR-34a/c-Met axis." (PMID 39401197, 2024). "Overexpression of NEAT1 induced downregulation of miR-34a in renal cell carcinoma (RCC) cells." (PMID 29036883, 2017). "However, in the tissues of renal cell carcinoma (RCC), METTL14 regulates the expression of NEAT1 through another recognition protein YTHDF2." (PMID 38654314, 2024).
diabetes (16 papers, 2017 to 2025). "For the differentially expressed lncRNAs identified, MIR7-3HG, LINC01116, HIF1A, MEG3, XIST, NEAT1, and HHLA3 have been previously associated with some form of diabetes and diabetes-associated complications." (PMID 38326874, 2024). "In the present study, we aimed to analyze the role of NEAT1 in human MCs (hMCs) in various in-vitro diabetes models." (PMID 35893235, 2022). "NEAT1 was also decreased in various in-vitro diabetes experiments treating hMCs with TGFβ, TNAα, TG, or TM." (PMID 35893235, 2022). "Diabetes-induced cardiomyocyte apoptosis can be mitigated via the activation of nuclear paraspeckle assembly transcript 1 (Neat1)/miR-140-5p/HDAC4 axis." (PMID 36552599, 2022). "In diabetes-induced renal injury, lncRNA nuclear enriched abundant transcript 1 (NEAT1) is found to be increased in the serum of DN patients." (PMID 34054586, 2021). "In patients with diabetes mellitus (DM) and myocardial cells and heart tissues from rats with high glucose-induced DM, NEAT1 was downregulated, and the expression levels of Nrf2 were decreased (p<0.01, p<0.001)." (PMID 34231706, 2021). "We focused on miR‐181b and miR‐144 and lncRNAs MALAT1 and NEAT1 due to their potential relationship with diabetes." (PMID 28643459, 2017). "We further validated two ceRNA pairs (MALAT1‐miR‐144‐mTOR and NEAT1‐miR‐181b‐mTOR) involved in mTOR pathway and explored their significance in diabetes mellitus." (PMID 28643459, 2017). "Our goal was to investigate the role of NEAT1 in hMCs in various in-vitro diabetes models." (PMID 35893235, 2022). "In addition, according to immunofluorescence staining of MTs, metformin, a medicine for the treatment of diabetes mellitus, rescued the reduced length of neurites detected in NEAT1 silencing cells." (PMID 33221742, 2020). "We only focused on lncRNA MALAT1 and NEAT1 considering their potential role in diabetes." (PMID 28643459, 2017). "In this study, we investigated the expression of nuclear paraspeckle assembly transcript 1 (NEAT1), a highly conserved lncRNA, in several diabetes in-vitro models using human MCs." (PMID 35893235, 2022). "A report has indicated that the overexpression of miR-342-3p following inhibition of NEAT1 decreases the release of the inflammatory cytokines IL-6, IL-1β, TNF-α, and cyclooxygenase-2 in type 1 diabetes mellitus." (PMID 36310619, 2022). "We demonstrated that NEAT1 was significantly upregulated in both bovine serum albumin (BSA)-stimulated HK2 cells and mice with HFD- and STZ-induced diabetes." (PMID 32054986, 2020). "Increased circulating expression of NEAT1 lncRNA has been reported in type 2 diabetic patients, while the role of AC015813.1 lncRNA in diabetes is not known." (PMID 39464889, 2024).
ischemic stroke (16 papers, 2020 to 2025). A stroke disorder caused by obstruction of blood flow to the brain, due to thrombotic (local blood clot formation) or embolic (due to a blood clot or other material traveling from another site) event. "The present study strived to shed novel light on the complex machinery underlying NEAT1-associated signaling pathways with regard to ischemic stroke." (PMID 38212456, 2024). "Inhibition of lncRNA NEAT1 attenuates neuronal injury, decreases infarct size and improves ischemic stroke." (PMID 38515760, 2024). "We assessed the possibility that methyltransferase METTL3 is involved in regulating NEAT1 m6A modification in ischemic stroke by MeRIP-qPCR." (PMID 38180752, 2024). "Among these lncRNA, the nuclear paraspeckle assembly transcript 1 (NEAT1) is a viable target for future therapy of ischemic stroke." (PMID 38212456, 2024). "To further clarify the role of NEAT1 in ischemic stroke, we explored the effects of NEAT1-regulated microglial polarization on the neovascularization capacity of cerebrovascular endothelial cells and the underlying molecular regulatory mechanisms." (PMID 38684954, 2024). "Our results confirm that the pharmacological activity of berberine in alleviating ischemic stroke is associated with Nampt, and reveal the associated mechanism of METTL3 and NEAT1 from the viewpoint of m6A modification." (PMID 38180752, 2024). "This suggests that lncRNA NEAT1 is engaged in ischemic stroke, however the exact mechanism by which lncRNA NEAT1 regulates ischemic stroke remains to be explored." (PMID 38180752, 2024). "Coincidentally, it has been suggested that NEAT1 alleviate ischemic stroke inhibiting NLRP3 mediated via miR-10b-5p/BCL6 axis." (PMID 36941678, 2023). "Jin (2021) confirmed by bioinformatics analysis and experiments that Neat1 promotes the activation of microglia and promotes inflammatory response in the pathological process of ischemic stroke." (PMID 36275741, 2022). "In our study, the lncRNA NEAT1 was expressed at higher levels in patients with ischaemic stroke than in normal subjects and was related to the cerebral infarct volume." (PMID 33184298, 2020). "The expression of the lncRNA NEAT1 was significantly upregulated in patients with ischaemic stroke, and knockdown of the lncRNA NEAT1 alleviated OGD/R-induced apoptosis and increased neuronal viability." (PMID 33184298, 2020). "Previous studies have shown that lncRNA NEAT1 promotes OGD/R-induced neuronal damage, suggesting that lncRNA NEAT1 may be involved in ischemic stroke." (PMID 40458797, 2025). "The intraventricular injection of an antisense oligonucleotide to knock down NEAT1 significantly reduced brain damage by reducing activated microglia and proinflammatory cytokines in a mouse model of ischemic stroke, supporting NEAT1 as a potential therapeutic target for ischemic stroke treatment." (PMID 40362651, 2025). "Similarly, in ischemic stroke, NEAT1 promotes ferroptosis by acting as a ceRNA, sponging miR-17-5p, and enhancing TLR4 expression." (PMID 41268533, 2025). "The lncRNA NEAT1 regulates NLRP3 inflammasome activation in microglia by forming a NEAT1/miR-10b-5p/BCL6/NLRP3 axis, thereby mitigating the harmful outcomes of ischemic stroke-induced inflammation." (PMID 39847586, 2025). "Furthermore, regulating the MIAT/EGLN2 axis and NEAT1/EGR1/RBM25 axis provides therapeutic strategies for ischemic stroke therapy, and ETAR/miR-27b-3p/FBXW7/KLF5/GLI1 axis and miRNA-146-5p/USP3 axis may act as potential targets for PAH prevention and treatment." (PMID 38515760, 2024). "NEAT1 overexpression promoted neuronal survival in ischemic stroke by regulating the MFN2/ SIRT3 pathway 241, whereas NEAT1 knockdown increased neuronal survival by inhibiting M1 microglia polarization via the Akt/ STAT3 pathway." (PMID 35966580, 2022).
ischemic stroke (continued). "A previous study was performed on the plasma samples from patients with ischemic stroke, and up-regulated levels of lncRNAs including H19, MIAT, ANRIL, MEG3 and NEAT1 were detected." (PMID 33613191, 2020). "Furthermore, several studies reported that the lncRNA Neat1 was increased in an MCAO/R animal model, an OGD/R-induced cell model, and ischemic stroke patients." (PMID 35991562, 2022). "However, the role of NEAT1-regulated microglial polarization in the damage and repair of brain tissue resulting from ischemic stroke was not fully revealed." (PMID 38684954, 2024). "In summary, lncRNA-Neat1 is abnormally up-regulated in MCAO, which activates microglia and plays a pro-inflammatory role, and knockdown of Neat1 can improve the inflammatory response after ischemic stroke, reduce neuronal apoptosis and improve neurological function." (PMID 36275741, 2022).